FST (follistatin)
Diseases named in the same sentence as FST in open-access papers (continued):
Sharing a sentence is not in itself a finding about the gene and the disease.
inclusion body myositis (4 papers, 2017 to 2022). A slowly progressive degenerative inflammatory disorder of skeletal muscles characterized by late onset weakness of specific muscles and distinctive histopathological features. "Another study evaluates the effects of intra-muscular injections of an isoform of follistatin (FS344) by AAV1 in combination with exercise in a small group of patients with inclusion body myositis." (PMID 30613464, 2018). "Furthermore, patients with inclusion body myositis show not only reduced myostatin expression levels in skeletal muscle but also an increased follistatin expression." (PMID 35922829, 2022).
osteoporosis (4 papers, 2013 to 2025). A condition of reduced bone mass, with decreased cortical thickness and a decrease in the number and size of the trabeculae of cancellous bone (but normal chemical composition), resulting in increased fracture incidence. "In contrast, a recent study demonstrated that higher circulating follistatin concentrations in women with postmenopausal osteoporosis compared with a healthy premenopausal group were negatively correlated with measured aBMD values." (PMID 37508723, 2023). "Accordingly, it was thought that follistatin could be related to osteoporosis in postmenopausal women and that it should be investigated further to find out whether follistatin could be used as a therapeutic target for low aBMD." (PMID 37508723, 2023).
acne (3 papers, 2021 to 2024). An inflammatory process of the sebaceous glands which is characterized by comedones, nodules, papules and/or pustules on the skin. "A recent analysis revealed that the follistatin (FST) rs629725 A allele poses a significantly modest increased risk for acne vulgaris presentation." (PMID 39595602, 2024). "This systematic review and meta-analysis suggest that genes influencing inflammatory responses, specifically TNF, and genes influencing the function and activity of sebaceous glands, specifically CYP17A1 and FST, have potential risk variants for acne presentation and severity across populations." (PMID 33849530, 2021). "In addition, the activity of the TGFβ signaling pathway is regulated by the transcription factor OVOL1 and the protein follistatin (encoded by FST), thus variations in these genes may influence sebocyte lipid synthesis and thus play a part in acne development and exacerbation." (PMID 33849530, 2021).
acute kidney injury (3 papers, 2022 to 2024). Sudden and sustained deterioration of the kidney function characterized by decreased glomerular filtration rate, increased serum creatinine or oliguria. "We then compared the localization of follistatin and acute kidney injury (AKI) biomarkers such as KIM-1 and NGAL in ischemic kidneys." (PMID 36899937, 2023). "In this study, we investigated the localization of follistatin in the normal human kidney and its potential utility as a marker for acute kidney injury (AKI)." (PMID 38534369, 2024). "In the injected mice, activation of the follistatin (Fst), utrophin, or klotho genes was shown to increase the muscle mass or mitigate the muscle wasting phenotype (e.g., Duchenne muscular dystrophy) or, in the case of klotho, to attenuate the disease phenotype of acute kidney injury." (PMID 35152318, 2022). "In a comparative analysis of urinary follistatin and other acute kidney injury (AKI) biomarkers, we observed a significant correlation between urinary follistatin and urinary NGAL." (PMID 38534369, 2024).
Anxiety (3 papers, 2008 to 2025). Intense feelings of nervousness, tension, or panic often arise in response to interpersonal stresses. "Transgenic mice expressing Follistatin after 2 weeks of age, exhibit enhanced anxiety, as well as a decrease in the survival of newly formed neurons in the adult hippocampus." (PMID 22928036, 2012). "We explored the role activin plays in anxiety-related behavior using a transgenic mouse model that overexpresses activin or follistatin, an activin-inhibitory protein, in a forebrain-specific manner." (PMID 18382659, 2008). "Interestingly, few studies reaped success in sleep onset, inflammaging status, muscle growth factors (follistatin, actinin), anxiety and depression and executive functions among healthy older adults who have undergone classical RT programs." (PMID 40430117, 2025). "Moreover, mice with postnatal overexpression of Follistatin, driven by the neuronal forebrain αCaMKII promoter, presented increased anxiety-related behavior and decreased neurogenesis in the adult hippocampus." (PMID 22928036, 2012). "In this study, we demonstrate that activin modulates anxiety-related behavior by analyzing ACM4 and FSM transgenic mice in which activin and follistatin (which antagonizes the activin signal), respectively, were overexpressed in a forebrain-specific manner under the control of the αCaMKII promoter." (PMID 18382659, 2008).
breast disease (3 papers, 2009 to 2021). "FST is expressed in the normal mammary gland and proliferative breast disease." (PMID 34001106, 2021). "Follistatin and FLRG were expressed both in normal tissue and in all the breast diseases investigated." (PMID 19740438, 2009).
cardiac hypertrophy (3 papers, 2021 to 2025). "This is interesting, given that previous research has also described how variation in the delicate balance between follistatin/myostatin activity likely facilitates cardiac hypertrophy." (PMID 41132156, 2025). "Because follistatin is an inhibitor of myostatin, such a shift in follistatin/myostatin balance would facilitate the heart hypertrophy in the course of training." (PMID 38136649, 2023). "In addition, overexpression of FST promoted cardiac hypertrophy with an unchanged expression of atrial natriuretic peptide (ANP) and the ratio of myosin heavy chain-β/myosin heavy chain-α (MYH7/MYH6)." (PMID 34385917, 2021). "In addition, our results also revealed that FST overexpression increases cardiac hypertrophy in a compensatory manner." (PMID 34385917, 2021).
cervical cancer (3 papers, 2014 to 2023). A primary or metastatic malignant neoplasm involving the cervix. "To date, knowledge about the role of the activin–follistatin system in the progression of cervical cancer is limited." (PMID 37243119, 2023). "In the present study, we investigated the localization pattern and expression profile of βA-activin and follistatin during different stages of cervical cancer progression (from CIN1 to SCC) in unvaccinated women predominantly positive for HR-HPV infection." (PMID 37243119, 2023). "However, the understanding of the role of follistatin in the progression of cervical cancer is still quite limited." (PMID 37243119, 2023). "Previous studies also revealed that FST protein can be detected not only in the gonads and extragonadal tissues, but also in peripheral blood and cell culture supernatant, and serum FST levels were correlated to pregnancy and cervical cancer." (PMID 25347573, 2014). "Knowledge about the expression profile of the activin–follistatin system during CIN progression, predominantly positive for HPV, can positively impact strategies for the diagnosis and control of cervical cancer." (PMID 37243119, 2023). "Although Gal-7 affects the specific cervical cancer networks in different ways, we identified a group of eight molecules that are regulated in both cell lines: CRYAB, TACSTD2, BCL-3, COX19, OASL, CDKN2A/p14ARF, NIBAN/FAM129A, and FST." (PMID 27558259, 2016).
Cirrhosis (3 papers, 2008 to 2024). A chronic disorder of the liver in which liver tissue becomes scarred and is partially replaced by regenerative nodules and fibrotic tissue resulting in loss of liver function. "Levels of follistatin were studied in immune depleted serum from individuals with either NAFLD (n = 10), NAFLD with cirrhosis (n = 10), or NAFLD with cirrhosis and HCC (n = 10) by western blot analysis." (PMID 18638391, 2008). "Here we present the data on a cross-sectional study comparing the efficacy of these markers, as well as a novel candidate biomarker, Follistatin, for the diagnosis of HCC arising on a background of steatohepatitis related cirrhosis." (PMID 18638391, 2008). "While there was little evidence of follistatin in the serum of individuals with NAFLD without significant fibrosis or HCC, it was detectable in all indiduals with HCC as well as some individuals with cirrhosis and no HCC." (PMID 18638391, 2008).
endometrial cancer (3 papers, 2009 to 2021). Primary or metastatic malignant neoplasm involving the endometrium (mucous membrane that lines the endometrial cavity). "Conversely, in endometrial carcinoma, FST expression is unchanged while FLRG expression is down-regulated." (PMID 19740438, 2009).
fibrosis (3 papers, 2013 to 2025). the formation of excess fibrous connective tissue in an organ or tissue in a reparative or reactive process. "The major follistatin transcript variants were found to have a similar response to IR and both were reduced in fibrosis patients." (PMID 24204752, 2013). "Follistatin treatment has been found to inhibit bleomycin-induced lung inflammation and subsequent fibrosis, indicating that blocking activin function can be beneficial." (PMID 25361680, 2014). "Both follistatin and activin A gene expression levels were increased following IR and the follistatin gene expression level was lower in the fibroblasts from fibrosis patients compared to controls at both basal levels and after IR." (PMID 24204752, 2013). "Levels of follistatin and activin A secreted in the fibroblast culture medium also increased in response to IR and the relative follistatin protein levels were significantly lower in the samples derived from fibrosis patients." (PMID 24204752, 2013). "We also found that the levels of follistatin gene expression and protein secretion in fibroblasts were able to differentiate most of our radiation induced fibrosis patients from non-fibrosis patients." (PMID 24204752, 2013). "Our finding that follistatin at both the transcription and translation levels predicted fibrosis in most of our fibrosis patients provides a good candidate for predicting patient fibrosis susceptibility in the clinic." (PMID 24204752, 2013). "We found that follistatin and activin A respond to IR at the transcriptional and translational level, and the samples from patients who developed fibrosis had lower levels of follistatin." (PMID 24204752, 2013). "In fibrosis patients the decrease in follistatin may result in an increase in activity of activin A and myostatin possibly suppressing the apoptosis that occurs in myofibroblasts after IR-induced damage has been repaired." (PMID 24204752, 2013). "The FST expression levels were lower in all the fibrosis patients compared to all the controls." (PMID 24204752, 2013).
Glucose intolerance (3 papers, 2021 to 2025). Glucose intolerance (GI) can be defined as dysglycemia that comprises both prediabetes and diabetes. "However, in mice, emerging evidence suggests that ActRIIA/IIB blockade may disrupt glucose homeostasis, given that hepatic follistatin production caused glucose intolerance and Bimagrumab treatment elevated baseline blood glucose levels." (PMID 41022302, 2025).
Hepatic steatosis (3 papers, 2022 to 2025). Steatosis is a term used to denote lipid accumulation within hepatocytes. "The specific role of activins in hepatocytes is incompletely understood as activin A has been suggested to both protect hepatic tissue from adipose accumulation as well as induce hepatic steatosis in activin-antagonizing follistatin-deficient mice." (PMID 35024891, 2022). "The data suggest a synergistic relationship between follistatin and PAI-1 in the regulation of prothrombotic status in conditions of hepatic steatosis." (PMID 40647228, 2025).
liver diseases (3 papers, 2014 to 2015). "The expressions of activin subunits and follistatin have been reported in the liver and alteration in their expression has been linked with several liver diseases." (PMID 24799891, 2014). "Significant dysregulation in serum activin-A/follistatin axis also occurs during liver diseases and, therefore, could be utilized as diagnostic/prognostic biomarkers for liver injury." (PMID 25969625, 2015). "Hence, it has been suggested that activins are tightly regulated in the liver and pathological alterations in the activin-follistatin axis have been associated with several hepatic disorders including viral and nonviral diseases." (PMID 26236109, 2015).
ovarian tumors (3 papers, 2012 to 2025). "Hypothetically, FST overexpression could be beneficial in treating ovarian tumors with high expression of Activin." (PMID 22685544, 2012). "Next, we aimed to investigate the expression levels of FST and FSTL3 in human ovarian tumor tissues." (PMID 41029436, 2025).
pancreatic cancer (3 papers, 2016 to 2021). "Orthotopic pancreatic tumor model was employed to explore the effects on gemcitabine resistance with recombinant follistatin to block activin A." (PMID 33537082, 2021). "Results showed that purified recombinant human FST (30-317 aa) protein significantly inhibited activin A-induced Smad3 phosphorylation, decreased gemcitabine resistance and reduced gene expressions of pancreatic cancer stemness markers in gemcitabine resistant PDAC cells." (PMID 33537082, 2021).
pulmonary fibrosis (3 papers, 2013 to 2014). Chronic progressive interstitial lung disorder characterized by the replacement of the lung tissue by connective tissue, leading to progressive dyspnea, respiratory failure, or right heart failure. "Follistatin has been shown to suppress bleomycin-induced lung fibrosis and carbon tetrachloride-induced liver fibrosis in experimental mouse models." (PMID 25361680, 2014). "First, we identified by expression array screening that activin-B and follistatin are upregulated in human idiopathic pulmonary fibrosis (IPF)." (PMID 25361680, 2014). "We used specific antibodies for activin-A and -B subunits and follistatin to measure and localize their levels in idiopathic pulmonary fibrosis and control lung biopsies." (PMID 25361680, 2014). "For example, follistatin was found to reduce fibrosis in a bleomycin treated pulmonary fibrosis mouse model." (PMID 24204752, 2013). "Furthermore, follistatin exerted antifibrotic effects in bleomycin-induced pulmonary fibrosis." (PMID 24883308, 2014).
renal fibrosis (3 papers, 2014 to 2023). A final common manifestation of a wide variety of chronic kidney diseases characterized by glomerulosclerosis and tubulointerstitial fibrosis. "Our data demonstrate that miR299a-5p is an important post-transcriptional regulator of FST, with its upregulation an important pathogenic contributor to renal fibrosis." (PMID 33420269, 2021). "In their study, the inhibition of miR299a-5p was associated with the rise in FST expression in the kidneys of CKD mice and higher protection against renal fibrosis." (PMID 37760798, 2023). "Previously, we demonstrated that the antifibrotic protein follistatin (FST) is transcriptionally upregulated in cav-1 knockout MC and that its administration is protective against renal fibrosis." (PMID 33420269, 2021). "Collectively, these results are in keeping with a major role for FST in the protection against renal fibrosis seen with miR299a-5p inhibition." (PMID 33420269, 2021). "The present study demonstrated that the expression of activin A was significantly upregulated in the UUO kidneys and that recombinant follistatin prevented renal fibrosis in vivo." (PMID 24883308, 2014). "It has been suggested that an increase in FST expression/miR299a-5p inhibition may also diminish renal fibrosis via epigenetic regulation of histone deacetylase (HDAC)-mediated expression of profibrotic proteins." (PMID 37760798, 2023). "Whether therapeutic FST overexpression or miR299a-5p inhibition protects against renal fibrosis through the blockade of these alternative FST neutralization targets needs to be more thoroughly examined in future studies." (PMID 33420269, 2021). "Alternatively, FST expression/miR299a-5p inhibition may also reduce renal fibrosis through epigenetically regulating histone deacetylase (HDAC)-mediated expression of profibrotic proteins." (PMID 33420269, 2021). "First, follistatin attenuates renal fibrosis by blocking the action of TGF-β." (PMID 24883308, 2014). "In addition to antagonizing the profibrotic action of activin A, two mechanisms may explain the therapeutic effects of follistatin on renal fibrosis." (PMID 24883308, 2014). "Therefore, amelioration of renal fibrosis by follistatin may be obtained by the enhancement of the antifibrotic effects of BMP-7." (PMID 24883308, 2014). "The precise mechanism by which follistatin reduced renal fibrosis remains unclear in this study." (PMID 24883308, 2014).
rheumatoid arthritis (3 papers, 2012 to 2025). A chronic, systemic autoimmune disorder characterized by inflammation in the synovial membranes and articular surfaces. "Among the genes with the peak expression in the mid-pregnancy followed by a drop at term, BMP5, CDH11 and FST are implicated in bone and cartilage related disorders such as rheumatoid arthritis and osteoarthritis." (PMID 23145134, 2012). "Activin A and follistatin exhibit immunomodulatory functions, thus affecting autoinflammatory processes as found in rheumatoid arthritis (RA)." (PMID 31182152, 2019). "However, to date, there is a lack of studies regarding the potential role of follistatin in patients with rheumatoid arthritis and the limited information there is assesses a small number of number of patients." (PMID 40943156, 2025).
small cell lung carcinoma (3 papers, 2010 to 2015). Small cell lung cancer (SCLC) is a highly aggressive malignant neoplasm, accounting for 10-15% of lung cancer cases, characterized byrapid growth, and early metastasis. "FST, which is known as an activin-binding protein, suppress the metastasis of small cell lung carcinoma." (PMID 25942583, 2015).
squamous cell carcinoma (3 papers, 2014 to 2024). A carcinoma arising from squamous epithelial cells. "Cervical paraffin-embedded tissues from 162 patients sorted in control (n = 15), cervical intraepithelial neoplasia (CIN) grade 1 (n = 38), CIN2 (n = 37), CIN3 (n = 39), and squamous cell carcinoma (SCC; n = 33) groups were examined for βA-activin and follistatin immunostaining." (PMID 37243119, 2023). "Follistatin, a secreted glycoprotein and an endogenous bioneutralizer of TGF-β ligands, has gained prominence and emerged as a potentially targetable modulator of key resident cell populations in the tumor microenvironment, particularly in squamous cell carcinoma." (PMID 38392348, 2024).
allergic asthma (2 papers, 2015 to 2019). A asthma with a basis in a pathological type I hypersensitivity reaction. "Follistatin has mainly been described as an anti-inflammatory component inhibiting experimental induced allergic asthma and inflammatory bowel disease in mice by blocking activin A." (PMID 31182152, 2019). "In a murine model of allergic asthma, follistatin was preformed in the normal lung and then released together with activin A, suggesting that it serves as an endogenous regulator." (PMID 26030615, 2015).
Arthritis (2 papers, 2014 to 2016). Inflammation of a joint. "In this study, we examined the anti-inflammatory and anticatabolic effects of follistatin on a carrageenan-induced mouse arthritis model." (PMID 25574420, 2014). "To test this hypothesis, we examined the effects of follistatin in a carrageenan-induced mouse arthritis model." (PMID 25574420, 2014). "To test this hypothesis, we examined the effect of recombinant mouse follistatin protein in the carrageenan-induced arthritis model." (PMID 25574420, 2014).